RFPL4A (ret finger protein like 4A)
Synonyms: RFPL4; RNF210
Tractability: PROTAC: ubiquitination databases record sites on it.
Gene: Protein-coding gene on chromosome 19 (55,759,043 to 55,763,424, forward strand). Ensembl gene ENSG00000223638.
Subcellular location: Cytoplasm; Nucleus
Subcellular location (Human Protein Atlas): Centrosome; Cytosol
Gene Ontology:
Molecular function: protein binding; ubiquitin protein ligase activity
Biological process: innate immune response; regulation of gene expression
Cellular component: cytoplasm; nucleus
Genetic constraint (gnomAD): Loss-of-function variants: 4 observed, 7.19 expected, observed/expected ratio (o/e) 0.56, 90% interval 0.27 to 1.27. That is too few expected variants to judge how well the gene tolerates losing a copy. Missense variants: 111 observed, 240.8 expected, observed/expected ratio (o/e) 0.46, 90% interval 0.39 to 0.54. Synonymous variants: 43 observed, 88.43 expected, observed/expected ratio (o/e) 0.49, 90% interval 0.38 to 0.63.
Homologues: Orthologues: macaque RFPL4A (88% identical), dog RFPL4A (61% identical), mouse Rfpl4 (54% identical). Paralogues in human: RFPL4AL1 (99% identical), RFPL1 (57% identical), RFPL3 (57% identical), RFPL2 (55% identical), RFPL4B (30% identical), RNF135 (23% identical), SPRYD4 (11% identical), CD274 (7% identical), RNF152 (7% identical), CD86 (7% identical), PDCD1LG2 (6% identical), CD80 (5% identical).
Diseases named in the same sentence as RFPL4A in open-access papers:
RFPL4A is named in the same sentence as 3 diseases in open-access papers, as found by Europe PMC text mining. Sharing a sentence is not in itself a finding about the gene and the disease. The quoted sentences say what the papers report.
cancer (2 papers, 2015 to 2024). A tumor composed of atypical neoplastic, often pleomorphic cells that invade other tissues.
infection (2 papers, 2023 to 2025). The state of being infected such as from the introduction of a foreign agent such as serum, vaccine, antigenic substance or organism. "Western Blot as well as qRT-PCR experiments further confirmed the expression of DUX4 and known DUX4-target genes TRIM48, TRIM49, ZSCAN4, ZSCAN5a, ZSCAN5d and RFPL4A upon HSV-1, HCMV and KSHV-infection 25 in different experimental settings." (PMID 38168299, 2023).
RFPL4A also shares sentences with these, for which no sentence is quoted: colorectal cancer (1 paper).